RNA5SP534 (RNA, 5S ribosomal pseudogene 534)
Gene: Ribosomal RNA gene on chromosome 1 (207,708,898 to 207,708,981, reverse strand). Ensembl gene ENSG00000274059.
Homologues: Orthologues: chimpanzee 5S_rRNA (100% identical), guinea pig 5S_rRNA (44% identical), mouse Gm54615 (15% identical). Paralogues in human: RNA5SP150 (62% identical), RNA5S1 (61% identical), RNA5S10 (61% identical), RNA5S11 (61% identical), RNA5S12 (61% identical), RNA5S13 (61% identical), RNA5S14 (61% identical), RNA5S15 (61% identical), RNA5S16 (61% identical), RNA5S17 (61% identical), RNA5S2 (61% identical), RNA5S3 (61% identical), and 26 more.